EGF (epidermal growth factor)
Diseases named in the same sentence as EGF in open-access papers (continued):
Sharing a sentence is not in itself a finding about the gene and the disease.
tumor (continued). "These cytokines not only prevent apoptosis but also promote the proliferation of tumor cells, mainly through EGF secreted by TAMs." (PMID 38557942, 2024). "As a summary of this research, we proposed that active RSK2 phosphorylates cGAS at Ser120 and Thr130 by tumor promoters, such as EGF and bFGF." (PMID 39424777, 2024). "In this work, we show that GBM cells produce TSLP when stimulated with EGF, a crucial growth factor prevalent in this tumor microenvironment." (PMID 38557942, 2024). "First, TAMs secrete CSF‐1 in a paracrine manner to activate EGF signalling pathway in tumour cells, thereby inducing angiogenesis and distant metastasis of tumour cells." (PMID 38774995, 2024). "TAMs promote the formation of invadopodia by secreting EGF, which activates the EGF receptor in tumor cells." (PMID 39555068, 2024). "TAM-derived EGF then binds to the EGF receptor on tumor cells, leading to increased CSF1 production and activation of pathways associated with migration." (PMID 39555068, 2024). "In our model, TSLP production is induced only when cells are stimulated with EGF, suggesting a potential loop mechanism or positive feedback between the effects of EGF on the tumor and TSLP production." (PMID 38557942, 2024). "Tumor cells secrete CSF-1 and TAMs secrete epidermal growth factor (EGF) to enable both cell types to co-migrate along collagen fibers in an alternating fashion." (PMID 39588367, 2024). "For example, in C7 and C8 tumor clusters, outgoing pattern 1 coordinates signals like MK, EGF, PTN, GDF, and EDN." (PMID 38191424, 2024). "Gefitinib, a specific antagonist of receptor tyrosine kinase for epidermal growth factor, had the ability to inhibit tumor angiogenesis, suppress cell division and promote apoptosis." (PMID 38581057, 2024). "To this end, we first cultured tumor cells from spontaneous MB of Math1-cre/Ptcfl/fl mice as neurospheres (MB Stem-Like Cells, MB-SLCs) in EGF- and bFGF-free cultured medium to retain the characteristic of in vivo SHH-MB." (PMID 38062245, 2024). "A paracrine EGFR/CSF-1R interaction exists between TAMs and tumor cells in which CSF-1 stimulates macrophages to release EGF, leading to tumor cell proliferation and migration." (PMID 39003350, 2024). "Using hydrogels to lower EGF concentration around tumors is a promising strategy to inhibit tumor growth and recurrence." (PMID 39346915, 2024). "EGF also stimulates CSF-1 secretion by cancer cells, forming a positive feedback loop between macrophages and tumor cells." (PMID 39003350, 2024). "Here, we were able to determine that both human cell line U251 and tumor cells obtained from the biopsy of a patient with GBM (GBM-b) express TSLP when activated with EGF, a crucial growth factor prevalent in this tumor microenvironment." (PMID 38557942, 2024). "This interaction drives TAMs to secrete anti-inflammatory cytokines, such as TGF-β and IL-10, as well as pro-tumor factors like VEGF and EGF, thereby supporting tumor growth, promoting angiogenesis, and suppressing immune responses." (PMID 39575419, 2024). "Here, we show that sine oculis homeobox 1 (SIX1) phosphorylation integrates growth factors (e.g. TGFβ, EGF) to control aerobic glycolysis and determines its tumor-promoting activity." (PMID 39617783, 2024). "The epidermal growth factor (EGF) family is another crucial component that contributes to tumor angiogenesis through both direct and indirect effects." (PMID 39013849, 2024). "EGFR can be activated by epidermal growth factor (EGF) and then lead to the promotion on tumor cells proliferation and migration via inducing EMT." (PMID 39092293, 2024). "Comparing changes in absolute cytokine levels for IFNγ and the IFNγ-inducible cytokines CXCL9 and CXCL10 to the tumor-related cytokines EGF, HGF and VEGF highlights the strong treatment related effects for IFNγ-pathway related cytokines." (PMID 38454126, 2024).
tumor (continued). "While the tumor cells release CCL2 to recruit monocytes and induce their differentiation and polarization to M2 macrophages, the latter release epidermal growth factor (EGF) that upregulates CCL2 expression in tumor cells." (PMID 37711747, 2023). "For example, macrophages can secrete vascular endothelial growth factor (VEGF) and epidermal growth factor (EGF) that promote tumor growth." (PMID 37484024, 2023). "Cetuximab is a recombinant human/mouse chimeric IgG1 monoclonal antibody that specifically binds to EGFR on both normal and tumor cells, competitively inhibiting the binding of epidermal growth factor (EGF)." (PMID 38067203, 2023). "The expression levels of MMP9, VWF, VEGFA, SERPINE1, and TIMP1 in ccRCC tissues were higher than those in normal tissues, while the expression of EGF in tumor tissues was lower." (PMID 36959648, 2023). "In terms of the PSC function, CTHRC1 treatment markedly increased the genetic expression of tumor-promoting growth factors (EGF, HGF, and FGF by 4.9, 4.4, and 10.5 times, respectively) and cytokines (IL8 and IL10 by 3.7 and 2.9 times, respectively)." (PMID 37444482, 2023). "It was found that the gradient created by the EGF microcapsules increased the proliferation, expansion, and directional movement of the tumor cells." (PMID 37241602, 2023). "One such mechanism involves the release of CSF-1 from tumor cells attracting monocytes to the tumor environment, and the activation of EGF signaling promoting the migration of tumor cells." (PMID 37108109, 2023). "Epidermal growth factor (EGF) signaling activation is essential for tumor cell growth, survival, and progression." (PMID 37397476, 2023). "Anti-EGFR VHHs effectively inhibit proliferation of tumor cells in vitro and outgrowth of solid tumors in vivo by blocking EGF-mediated signaling." (PMID 37746282, 2023). "Subsequent investigation has elucidated that EGF secreted by TAMs engages with CSF1 released by tumor cells facilitating the migratory capabilities of the tumor cells." (PMID 38035101, 2023). "The M2 macrophages migrate towards nearby blood vessels, up spatial gradients in CXCL12, and the CSF-1/EGF paracrine loop enables tumour cells to trail behind them." (PMID 36972297, 2023). "Due to its role as a chemokine in the cancer microenvironment, EGF hastens metastasis by increasing tumor cell motility and invasiveness." (PMID 37138860, 2023). "We further showed that cadherin EGF LAG seven-pass G-type receptor 3 (CELSR3) knockdown results in reduced NEPC tumor cell proliferation and migration in vitro." (PMID 37546702, 2023). "Our model accounts for macrophage extravasation in response to tumour-derived CSF-1, their subsequent tumour infiltration, and the CSF-1/EGF paracrine loop that mediates cross-talk between tumour cells and macrophages." (PMID 36972297, 2023). "Tumor-associated macrophages (TAMs) release various angiogenic growth factors, with epidermal growth factor (EGF) being the most effective source of EGF in the tumor microenvironment." (PMID 37138860, 2023). "EGF was demonstrated to be antiapoptotic in tumor cells excessively expressing EGFR, a condition observed in the vast majority of solid tumors." (PMID 38090376, 2023). "TAMs can also facilitate tumor cell intravasation and extravasation by secreting epidermal growth factor (EGF) and vascular endothelial growth factor (VEGF)." (PMID 36845095, 2023). "Macrophages and tumor cells participate in a cross-communication paracrine loop in which TAMs express EGF which signals on tumor cells, while reciprocally tumor cells express CSF1 which promotes macrophage chemotaxis, differentiation, and survival." (PMID 37199172, 2023). "In this study, the galectin-3-mediated tumour cell-cell homotypic aggregation and promotion of EGF-induced EGFR activation are seen to be significantly reduced following C1GalT1-suppression." (PMID 37612278, 2023).
tumor (continued). "Overexpression and mutation of EGFR leads to constitutive activation of the EGF/EGFR pathway, which is associated with increased tumor proliferation and chemotherapy resistance and remains a major clinical challenge for cancer therapy." (PMID 37762316, 2023). "Increased cell migration and invasion are promoted by interactions between the tumor cell surface epidermal growth factor (EGF) receptors and its ligand EGF via upregulating MMP-2 expression." (PMID 37798646, 2023). "TIMER analysis showed that DNAJB1, COL10A1, PTGS2, AFP, and EGF were correlated with tumor-infiltrating lymphocytes." (PMID 36967783, 2023). "This method significantly increased the accumulation of EGF@DOX-NPs in the tumor tissues (0.68 ± 0.08 μg/mL of RT + EGF@DOX-NPs vs. 0.11 ± 0.07 μg/mL of free DOX) which resulted in superior tumor inhibition effects." (PMID 37415158, 2023). "They act on targets such as IL-6, FOS, STAT3, ERBB2, and EGF, exerting effects on delaying tumor cell resistance and inhibiting tumor cell invasion and metastasis." (PMID 37990309, 2023). "TAMs can release various cytokines, such as TGF‐β and EGF, which not only promote tumor proliferation and transformation but also facilitate the establishment of a tumor tolerance microenvironment." (PMID 36582304, 2023). "In this study, we report that LY6K‐depletion suppresses the effect of TGF‐β on invasiveness and EGF‐stimulated proliferation of tumor cells by repressing clathrin‐ and CAV‐1‐mediated endocytosis." (PMID 37076981, 2023). "In the tumor microenvironment, neutrophils secrete proteases, cytokines, and growth factors, including interleukin (IL)‐6, IL‐8, epidermal growth factor and vascular endothelial growth factor, that lead to tumor cell activation, invasion, and metastasis." (PMID 36806947, 2023). "Epithelial cells can acquire mesenchymal phenotypes under stimulation by tumor microenvironmental factors, such as epidermal growth factor, endothelin 1, and bone morphogenetic protein, leading to metastasis and invasion of tumor cells." (PMID 37528887, 2023). "On day 0, the tumor cells were completely dissociated into single cells and cultured in serum-free medium supplemented with EGF and bFGF." (PMID 36750863, 2023). "Here, it is demonstrated that eIF3f is upregulated in CRC tumor tissues and that both Wnt and EGF signaling pathways are participating in eIF3f's oncogenic impact on targeting phosphoglycerate dehydrogenase (PHGDH) during CRC development." (PMID 37544925, 2023). "CBs inhibited tumor invasion and metastasis in animal models and reduced EGF-induced proliferation and chemotaxis in triple-negative breast cancer cells." (PMID 37397476, 2023). "In solid tumor studies, including breast and lung cancers, TAMS promotes releasing tumor-derived CSF-1 and macrophage-derived EGF by invading tumor cells involving paracrine signaling circulation." (PMID 36999020, 2023). "TAMs were localized in the center of spheroids and secreted EGF, which upregulated the αMβ2 integrin on TAMs and ICAM-1 on tumor cells to promote association between tumor cells and TAMs." (PMID 37508575, 2023). "Compared with the control group, the expression levels of tumor metastasis-related genes EGF and EGFR were significantly increased in the MYL1 overexpression group." (PMID 37679666, 2023). "The possible mechanisms by which neutrophils promote tumor progression include changes in the microenvironment shaped by cancer cells and release of some growth factors, such as epidermal growth factor and hepatocyte growth factor." (PMID 36937347, 2023). "The signaling pathway driven by EGF/EGFR is an important regulator of tumor growth, invasion and metastasis in epithelial malignancies." (PMID 36960065, 2023). "It has also been revealed that MLT can inhibit the migration and invasion of epidermal growth factor (EGF)-induced MDA-MB-231 tumor cells by blocking the SDF-1α/CXCR4 and Rac1-mediated signaling pathways." (PMID 38017537, 2023).
tumor (continued). "ECM1 is a glycoprotein that can induce tumor growth by promoting angiogenesis or enhancing epidermal growth factor signaling." (PMID 37764869, 2023). "The hybrid ABM developed in this paper builds on existing differential equation models and ABMs that focus on specific tumour-macrophage interactions, such as the CSF-1/EGF paracrine loop that mediates cross-talk between tumour cells and macrophages." (PMID 36972297, 2023). "Subsequently, these recruited macrophages generate a panel of molecules (e.g., EGF, proinflammatory cytokines, and ROS) to reshape the microenvironment and facilitate tumor initiation." (PMID 38008741, 2023). "Since TGF‐β and EGF signals regulate tumor initiation and metastasis, elucidating LY6K expression during cancer progression is important." (PMID 37076981, 2023). "Tagging of EGF on these vesicles resulted in higher accumulation of the drug within the tumor sites and resulted in significant decrease in tumor size as compared to free drug." (PMID 38090593, 2023). "We showed that NANOG conferred anti-apoptotic phenotypes in response to anti-cancer agents by promoting autophagic EGF secretion in therapeutic-resistant tumor cells." (PMID 37165076, 2023). "Anemic hypoxia affects tumor metabolism by overexpressing hypoxia-inducible factor-1, vascular endothelial growth factor, glucose transporter, and epidermal growth factor." (PMID 36511609, 2023). "Macrophages promote tumor angiogenesis and an anti-immune response by emitting TNF-α, vascular endothelial growth factor, and epidermal growth factor, eventually leading to tumor progression." (PMID 37719125, 2023). "TAMs can augment tumor cell migration with epidermal growth factor (EGF), proliferation with platelet-derived growth factor (PDGF), and angiogenesis with vascular endothelial growth factor (VEGF)." (PMID 37569902, 2023). "EGF secreted by TAMs promotes tumor cell intravasation into blood vessels, while VEGF triggers endothelial cell barrier disruption by destroying adherens junctions." (PMID 36845095, 2023). "Similar results have been reported for the treatment of mice with visceral extract from the abalone Haliotis discus hannai, resulting in a significant inhibition of tumor metastasis through the regulation of Cox-2, EGF, VEGF, and FGF expression levels." (PMID 37704667, 2023). "SPT is reported to be a stronger inhibitor of EGF-driven cellular propagation in different tumor cell lines compared to gefitinib, the first-line clinical TKI." (PMID 36903565, 2023). "Then, TANs assist in tumor progression via the production of several cytokines and growth factors involved in tumor growth, including the epidermal growth factor, hepatocyte growth factor, and platelet-derived growth factors (PDGFs)." (PMID 37444436, 2023). "In order to assess the effect of cisplatin on scavenging function of TAMs, the acLDL was used as a general ligand of scavenging receptors, and EGF was used as a tumor-specific ligand." (PMID 36960065, 2023). "TAM release factors such as TGFβ, IL-1β, IL-6, stress-inducible protein 1 (STI1), and epidermal growth factor (EGF) that stimulate tumor growth and invasion." (PMID 37355636, 2023). "CRM197 has also been conjugated to epidermal growth factor (EGF) to create the EGF-CRM197 vaccine as a potential anti-tumor vaccine for cancers that secrete high levels of EGF." (PMID 37755989, 2023). "High CSC plasticity, the ability to transform and change in response to various signals from the TME, including hypoxia, transforming growth factor beta (TGFβ, and epidermal growth factor (EGF)) contribute to tumor growth." (PMID 37445860, 2023). "Nanobody-based targeting of tumor ligands, including EGF, HGF, and VEGF, has resulted in efficient inhibition of tumor growth and metastasis." (PMID 36761751, 2023).
tumor (continued). "In the epidermal growth factor (EGF)/epidermal growth factor receptor (EGFR) signal transduction pathway related to tumor invasion, GLUT1 is positively correlated with the expression of the EGFR HER-2 and tumor vascular EGF." (PMID 37542344, 2023). "U87MG cells were treated with 10 ng/mL EGF (positive control) and 100 μg/mL LHT7 because the VEGF and EGF pathways are closely related, sharing downstream signaling pathways in tumor cell proliferation." (PMID 37723574, 2023). "TAMs are responsible for secreting tumor-inducing factors, such as EGF (epidermal growth factor), thereby creating an immunosuppressive environment, and promoting angiogenesis, thereby maintaining tumor-related inflammation and inducing metastasis." (PMID 37373398, 2023). "We characterize the critical regulators of the FASN overexpression in tumor development, including EGF, CSN6, GSK3β, and E3 ligase FBXW7β." (PMID 37202390, 2023). "Our data demonstrated that cisplatin affects important elements of endocytic machinery in TAMs that correlates with impaired endocytic clearance of tumor supporting factor EGF from TME." (PMID 36960065, 2023). "To verify the potential role of EGF in the NANOG-mediated cisplatin resistance in tumor cells, we neutralized EGF with a specific monoclonal antibody in CaSki NANOG cells." (PMID 37165076, 2023). "Previous research has demonstrated that tumor cells synthesize CSF-1 to induce macrophage migration, and these macrophages can secrete EGF to stimulate tumor cell migration." (PMID 37359527, 2023). "For instance, autocrine EGF has been reported to significantly promote tumor growth and invasion in colorectal cancer." (PMID 37291128, 2023). "On the one hand, TAMs can promote tumor replication and invasion through colony-stimulating factor 1 and epidermal growth factor, on the other hand, they can express immunosuppressive factors like interleukin to facilitate the immune escape of tumor cells." (PMID 38264667, 2023). "As they migrate out of the tumour, the pro-tumour macrophages express epidermal growth factor (EGF), a tumour cell chemoattractant." (PMID 36972297, 2023). "The healing process of the trauma further increases the expression of epidermal growth factor, thus accelerating tumor deterioration." (PMID 37916176, 2023). "EGFR expression was higher in TNBC, EGFR overexpression leads to tumor cells receiving stimulus from cytokines, like heparin-binding-EGF, which are formed by the vascular endothelium, and the tumor cells are attached to the tissue with the help of selectins." (PMID 38090376, 2023). "CCL5 and EGF can induce tumor cell invasion by promoting IL-8 secretion from tumor cells via Akt signaling activation." (PMID 35936717, 2022). "For example, VEGF and EGF that are secreted by M2 macrophages (tumor-resident macrophages) induce angiogenesis and recruitment of neutrophils which upgrade tumor progression and metastasis." (PMID 35681234, 2022). "Knocking down ARF6 blocks EGFR sorting to PM, causes degradation of EGFR, disrupts EGF-induced EGFR signaling, and inhibits the growth of EGFR-overexpression tumor cells." (PMID 36224181, 2022). "According to the RNA-seq analysis, NRP2, NODAL, and NR2F2 were highly expressed, while EGF was lowly expressed in tumour tissue." (PMID 36172369, 2022). "More recently, Yoon et.al applied NRG1(neuregulin 1) to take place of EGF in tumor organoid media, to improve the luminal cell components for SGTs organoids." (PMID 36527158, 2022). "We find that the most upregulated proteins in control tumors compared to shINHA tumors were a subset of pro-angiogenic cytokines: IL-8 (2.5 times) and EGF (2.1 times) indicating a pro-angiogenic profile of the tumor cells in the presence of inhibin." (PMID 35654828, 2022).